PTCH2 (patched 2)
Diseases named in the same sentence as PTCH2 in open-access papers (continued):
Sharing a sentence is not in itself a finding about the gene and the disease.
tumor (33 papers, 2008 to 2025). "Deletion of the SUFU locus in 25/118 tumours (21%) was associated with marked upregulation of the Patched 2 tumour suppressor (PTCH2)." (PMID 34580349, 2021). "In the Hh signaling pathway, Ptch1 is regard as the primary regulator, but the concurrent loss of both Ptch1 and Ptch2 results in more severe tumorigenesis than the loss of Ptch1 alone, highlighting the cooperative role of these two proteins in tumor suppression." (PMID 39900571, 2025). "However, loss of PTCH2 markedly affected tumor formation in combination with PTCH1 haploinsufficiency." (PMID 19032739, 2008). "Bioluminescence imaging demonstrated a marked reduction of tumor cell proliferation, while levels of GLI1 and PTCH2 transcripts were reduced in cells from tumor samples." (PMID 31480477, 2019). "Modest perturbations of Ptch2 are apparently tolerated, resulting in sufficient Hh pathway upregulation in vivo to boost tumor growth, as evident from the enhanced tumor growth found for the Ptch2MED cells." (PMID 29869097, 2018). "We conclude that like Ptch1, Ptch2 exerts a tumor-suppressive function in BCC cells, and that after targeting of both paralogs, ligand-independent activation of the Hh pathway contributes to tumor growth." (PMID 29869097, 2018). "As expected, the expression level of both PTCH1 and PTCH2, which code for the receptors Ptch1 and Ptch2, was lower in tumour samples than in normal tissue, possibly participating in the Hh pathway activation." (PMID 22361633, 2012). "This chromosomal region is often deleted in certain reproductive cell tumors, indicating that PTCH2 may act as a tumor suppressor." (PMID 39900571, 2025). "In summary, Ptch1 and Ptch2 may play an important role in tumor inhibition, and their functions overlap but are unique." (PMID 39900571, 2025). "Ptch1 and Ptch2, both crucial in suppressing tumor growth in basal cell carcinoma (BCC) cells." (PMID 39900571, 2025). "In addition, a frameshift deletion in PTCH2 was identified at exon 15, likely explaining the reduced expression levels and at least a contribution to the higher tumor penetrance compared to Gorlin 2 NES cells." (PMID 31204176, 2019). "From the increased baseline pathway activity and associated tumor growth following Ptch2 targeting in vivo, we conclude that Ptch2 exerts ligand-independent pathway inhibitory functions that make it a tumor suppressor, but one that is also required and essential for cancer cell viability." (PMID 29869097, 2018). "Whether such a putative tumor suppressor function of Ptch2 may be uncoupled from its ligand binding function is currently unknown and is possibility complicated by the fact that these functions are connected." (PMID 29869097, 2018). "However, as we find that Ptch2 has a very limited ligand-perceiving role in BCC, we assume that its main function as a tumor suppressor is overshadowed by the loss of Ptch1, which is a stronger inhibitor of the Hh pathway." (PMID 29869097, 2018). "Next, we tested the contribution of Ptch2 to in vivo tumor growth using a xenograft model and found that reduced Ptch function results in increased tumor growth, but that selective pressure appatently acts against complete Ptch2 ablation." (PMID 29869097, 2018). "Interestingly, the genes of SUFU, Gli2, Wnt7a, and PTCH2 closely related to tumor cell proliferation were significantly upregulated." (PMID 28640224, 2017). "In this scenario, Ptch2 expression in endothelial cells might counteract the effects of SHH locally secreted by other cell types from the tumor mass, such as astrocytes and stromal cells." (PMID 26635611, 2015). "PTCH1 and PTCH2 were under-expressed in, respectively, 31.0 and 43.7% of tumour samples." (PMID 22361633, 2012). "In addition, it remains to be established whether the identified tumor suppressive action of Ptch2 is also relevant for non- or pre-malignant cultured keratinocytes." (PMID 29869097, 2018).
tumor (continued). "Collectively, our data suggest that Ptch2 upregulation in endothelial cells and further ligand activation cause an imbalanced HH signaling, that can account for the observed vascular dysfunctions and barrier disruption, while sparing SHH positive impact on tumor cell expansion." (PMID 26635611, 2015). "Next, we compared the expression levels of various HH target genes (GLI1, PTCH1, and PTCH2) in normal human primary esophageal epithelial cells and EAC cell lines derived from tumor samples." (PMID 32913560, 2020). "At the molecular level, the transcriptional factor GLI induces several genes involved in tumor progression, and the transmembrane proteins PTCH1 and PTCH2 act as pathway inhibitors." (PMID 33271924, 2020). "Patched 2 (PTCH2) is a second patched member, structurally similar to PTCH1, whose role as a tumour suppressor and response to Hh ligand have yet to be entirely understood." (PMID 31988301, 2020). "Here, we have untangled these functions by first delineating the signaling capabilities of Ptch2 in BCC cells in vitro and subsequently testing the consequences of Ptch2 perturbation for in vivo BCC tumor growth." (PMID 29869097, 2018). "PTCH1+/-PTCH2-/- and PTCH1+/-PTCH2+/- animals showed a higher incidence of tumors and a broader spectrum of tumor types compared with PTCH1+/- animals." (PMID 19032739, 2008). "In addition to the CNV analysis, we also utilized high PTCH1 and PTCH2 expression (PTCH1/2 high) in comparison to the healthy skin cluster hKC to pinpoint BCC tumor cells." (PMID 39516494, 2024). "Interestingly, we found that tumor cell proliferation-related genes of Wnt7a, SUFU, PTCH2, and Gli2 changed significantly." (PMID 28640224, 2017). "Overall, our work unveils a role for DHH in heightened tumor angiogenesis and permeability, which may ultimately favor GBM progression, and thus places the DHH/Ptch2 nexus as a putative target for novel therapies directed against malignant stem-cell niches in GBM." (PMID 26635611, 2015). "Independent of tumor characteristics, such as histology and grades, higher expressions of SHH, PTCH1, PTCH2, and GLI1 have shown beneficial prognostic influence, whereas GLI2, GLI3, and SUFU are correlated with adverse clinical outcomes in OC patients." (PMID 40565349, 2025). "Thus, it seems possible that the tumor suppressive effect of WIF1 overexpression on ASZ001 cells may be exerted, at least in part through the inhibition of non-canonical Shh signaling mediated by Ptch2." (PMID 34944004, 2021).
cancer (12 papers, 2016 to 2025). A tumor composed of atypical neoplastic, often pleomorphic cells that invade other tissues. "It thus appears that a low level of Ptch2 activity is required for cancer cell viability, at least in vitro." (PMID 29869097, 2018). "How these two counteracting activities are balanced remains to be determined, but it is possible that they are driven by distinct signaling functions of Ptch2 (Smo antagonist, chemotaxis receptor, dependence receptor), or by a cancer-specific context." (PMID 29869097, 2018). "Given that knockdown of PTCH2 was reported to exert significant growth inhibition in a clear cell cancer cell line, this gene might be in part responsible for the observed growth inhibitory effects of this ERβ agonist." (PMID 28482871, 2017).
infection (3 papers, 2022 to 2023). The state of being infected such as from the introduction of a foreign agent such as serum, vaccine, antigenic substance or organism. "We predicted an E. chaffeensis TRP120-Hh-SLiM and identified a direct interaction between TRP120 and PTCH2 during infection." (PMID 35576232, 2022). "Loss of PTCH2 receptor significantly reduced infection, while loss of PTCH1 receptor did not, suggesting that E. chaffeensis may preferentially target PTCH2 during infection." (PMID 35576232, 2022).
PTCH2 also shares sentences with these, for which no sentence is quoted: breast carcinoma (2 papers); coloboma (2); glioma (2); autosomal-dominant inherited disorder (1); brain disorder (1); CNS tumor (1); Down syndrome (1); endometrial cancer (1); fibroma (1); genetic disorder (1); holoprosencephaly (1); melanoma (1); neurodevelopmental disorder (1); neurofibromatosis (1); ovarian clear cell cancer (1); rhabdomyosarcoma (1); sex cord-stromal tumor (1); skin cancer (1); spinal cord injury (1); thyroid cancer (1).